MAN2B1 (mannosidase alpha class 2B member 1)
Diseases named in the same sentence as MAN2B1 in open-access papers (continued):
Sharing a sentence is not in itself a finding about the gene and the disease.
lupus (2 papers, 2019 to 2025). "Although distinguished phenotypically, this included non-lupus-related features such as dysmorphism and developmental delay and infection arising as part of the complex phenotype of the causal variants identified (MAN2B1, SLC7A7, PTEN, STAT1)." (PMID 40465409, 2025). "For instance, patient 3C (MAN2B1 and SLC7A7) presented with predominant lung involvement which is an extremely rare manifestation as the first presentation of lupus." (PMID 31362757, 2019).
osteosarcoma (2 papers, 2021 to 2023). A usually aggressive malignant bone-forming mesenchymal neoplasm, predominantly affecting adolescents and young adults. "Among them, MAN2B1, P4HA2, ANPEP, BCAT1, CTSS, and DAPK1 were significantly correlated with the prognosis of patients with osteosarcoma." (PMID 37457661, 2023).
anaplastic astrocytoma (1 paper, 2022). "Moreover, according to histopathological classification, higher expression of MAN2B1 was found in GBM than in astrocytoma, oligodendroglioma, oligoastrocytoma, and anaplastic astrocytoma (P<0.05)." (PMID 35186771, 2022).
autoimmune disease (1 paper, 2024). A disorder resulting from loss of function or tissue destruction of an organ or multiple organs, arising from humoral or cellular immune responses of the individual to their own tissue constituents. "Clinical evidence strongly associates MAN2B1 mutations with autoimmune diseases such as SLE and Sjögren’s syndrome." (PMID 39628046, 2024). "These clinical cases emphasise a strong association between mutations in MAN2B1 and autoimmune diseases." (PMID 39628046, 2024). "Indications are pointing towards a potential association between MAN2B1 and autoimmune diseases." (PMID 39628046, 2024). "Additionally, abnormal expression of MAN2B1 has been associated with various other diseases, encompassing congenital anomalous erythropoietic anaemia type II, cancers, infectious diseases, autoimmune diseases and neurodegenerative conditions." (PMID 39628046, 2024). "Intriguingly, the involvement of MAN2B1 in infections, nervous system, autoimmune disorders and organ damage shows certain correlations with symptoms observed in α-mannosidosis." (PMID 39628046, 2024).
beta-mannosidosis (1 paper, 2023). Beta-mannosidosis is a very rare lysosomal storage disease characterized by developmental delay of varying severity and hearing loss, but that can manifest a wide phenotypic heterogeneity. "The loss of enzymatic activities of other well studied family members, including lysosomal alpha-mannosidase (MAN2B1) and mannosidase beta (MANBA), resulted in alpha- and beta- mannosidosis." (PMID 35637269, 2023).
low grade glioma (1 paper, 2022). A grade I or grade II glioma arising from the central nervous system. "Moreover, MAN2B1 has shown to be over-expressed in both GBM and low-grade gliomas (LGGs) compared with normal brain tissue." (PMID 35186771, 2022).
macroglossia (1 paper, 2024). The presence of an excessively large tongue, which may be congenital or may develop as a result of a tumor or edema due to obstruction of lymphatic vessels, or it may occur in association with hyperpituitarism or acromegaly. "According to a published report, additional clinical manifestations including macroglossia, widely spaced teeth, a large head with a prominent forehead, dysostosis multiplex, flattened nasal bridge, rounded eyebrows, and motor impairment may also appear as a result of MAN2B1 variants." (PMID 39280098, 2024).
melanoma (1 paper, 2021). A malignant, usually aggressive tumor composed of atypical, neoplastic melanocytes. "Notably, MAN2B1 was expressed at the highest level in subjects with melanoma." (PMID 34544412, 2021). "MAN2B1 and ST3GAL4 exhibited higher expression in melanoma patients, and MAN2C1 was downregulated in tumor tissues." (PMID 34544412, 2021).
mucopolysaccharidoses (1 paper, 2023). "Beyond sphingolipid/ceramide metabolism, our screen also identifies many fly homologs of genes causing human mucopolysaccharidoses (e.g., GLB1, IDS, IDUA, MAN2B1, MANBA)." (PMID 37200393, 2023). "In an independent longitudinal proteomics dataset we replicated αSyn-induced increases among 6 of these proteins, including Npc1a and several proteins homologous to human LSD gene products causing mucopolysaccharidoses: GLB1/Ect3, MAN2B1/LManII, and MANBA/Beta-Man." (PMID 37200393, 2023).
promyelocytic leukemia (1 paper, 2022). "Also, a recent study found that the high α-D-mannosidase enzyme activity was associated with the MAN2B1 transcriptional upregulation in the promyelocytic leukemia cell lines." (PMID 35186771, 2022). "Similarly, elevated expression of MAN2B1 was also reported in promyelocytic leukemia cell." (PMID 35186771, 2022).
infection (8 papers, 2010 to 2025). The state of being infected such as from the introduction of a foreign agent such as serum, vaccine, antigenic substance or organism. "Infections, notably bacterial meningitis and peritonitis, displayed heightened lysosomal mannosidase activity, suggesting the involvement of MAN2B1 in bacterial-induced inflammation." (PMID 39628046, 2024). "Notably, MAN2B1 exhibits elevated expression in monocytes and dendritic cells, pivotal in the body’s immune defence against infections and inflammatory responses." (PMID 39628046, 2024). "Additionally, in Porcine Reproductive and Respiratory Syndrome Virus (PRRSV) infection of porcine alveolar macrophages, a cell type primarily targeted by the virus, MAN2B1 was among the genes showing significant downregulation." (PMID 39628046, 2024).
cancer (5 papers, 2021 to 2025). A tumor composed of atypical neoplastic, often pleomorphic cells that invade other tissues. "The subcellular localization of mutant MAN2B1 is well known to be associated with inherited metabolic diseases, while the role of MAN2B1 in cancers is unknown." (PMID 34544412, 2021). "To elucidate the MAN2B1 expression pattern in human cancers, we firstly evaluated MAN2B1 expression by analyzing TCGA pan-cancer RNA-seq data." (PMID 35186771, 2022). "While the correlation between α-D-mannosidase and Ras activation remains unreported in cancers, upregulation of MAN2B1 and heightened α-mannosidase activity have been documented in various cancers, including gynaecologic cancer, malignant glial tumours and leukaemia." (PMID 39628046, 2024). "In the TCGA pan-cancer cohort, MAN2B1 resulted as a prognostic factor for progression-free survival (PFS), overall survival (OS), disease-specific survival (DSS), and disease-free survival (DFS) in LGG, GBM, cervical squamous carcinoma (CESC), and kidney renal clear cell carcinoma (KIRC)." (PMID 35186771, 2022). "We first performed a pan-cancer survival analysis of MAN2B1 in the TCGA database." (PMID 35186771, 2022). "Moreover, HEXA, HEXB, MAN2A1, and MAN2B1 were overexpressed in cancer relative to healthy stomachs from individuals without gastric pathologies." (PMID 41041068, 2025).
metabolic disease (4 papers, 2019 to 2025). A congenital disorder (due to inherited enzyme abnormality) or acquired (due to failure of a metabolically important organ) disorder resulting from an abnormal metabolic process. "These additional putative mono/oligogenic SLE genes are involved in type I IFN regulation (DDX58, NLRC4 and PACSIN1), disruption of B cell and T cell tolerance (DOCK8, FAS and LRBA) and metabolic disorders (CYBB, MAN2B1, SLC7A7)." (PMID 40386946, 2025).
Tumor (4 papers, 2021 to 2025). "Further analysis confirmed that MAN2B1 was closely associated with the markers of M2 macrophages and tumor-associated macrophages." (PMID 35186771, 2022). "Furthermore, the correlation between MAN2B1 and tumour-associated macrophages indicates possible involvement of MAN2B1 in shaping the tumour microenvironment." (PMID 39628046, 2024). "Notably, MAN2B1 transcriptional regulation differs between normal and tumour cell lines." (PMID 39628046, 2024). "Notably, neoplasia patients exhibited a tendency to upregulate several glycogenes, including MGAT1, MAN2A1, MAN2B1, and MGAT2 (which contributed to the clustering), associated with the initial steps of the biosynthesis of more complex N-glycan structures." (PMID 40087977, 2025).
genetic disorder (3 papers, 2023 to 2025). "The absence of MAN2B1 in gene panels suggests that a whole-genome approach may be more effective for diagnosing genetic disorders." (PMID 41334501, 2025).
MAN2B1 also shares sentences with these, for which no sentence is quoted: cutaneous melanoma (2 papers); glioblastoma (2); Hearing impairment (2); pancreatic adenocarcinoma (2); astrocytoma (1); autoimmune disorders (1); bladder urothelial carcinoma (1); breast invasive carcinoma (1); cerebellar ataxia (1); cervical squamous cell carcinoma (1); clubfoot (1); COVID-19 (1); craniostenosis (1); craniosynostosis (1); developmental delay (1); esophageal carcinoma (1); Frank-Ter Haar syndrome (1); glaucoma (1); immune deficiency (1); laryngeal carcinoma (1); learning disability (1); Lipid storage disease (1); lysinuric protein intolerance (1); mucopolysaccharidosis type 7 (1); Neurodegeneration (1); Niemann-Pick disease type C (1); oligoastrocytoma (1); oligodendroglioma (1).